GPER1 (G protein-coupled estrogen receptor 1)
Diseases named in the same sentence as GPER1 in open-access papers (continued):
Sharing a sentence is not in itself a finding about the gene and the disease.
vulvar carcinoma (1 paper, 2023). "In both vulvar carcinoma cell lines, GPER1 was visible to the same extent in the nucleus and cytoplasm." (PMID 37762008, 2023). "Due to the limited evidence concerning the importance of GPER1 in the progression of vulvar carcinoma and the significance of the receptor as a therapeutic target, especially in gynecological neoplasms, it is further investigated in this study." (PMID 37762008, 2023). "Via Western blotting, the effects of treatment with GPER1 agonist G1 and antagonist G36 on estrogen receptor expression in vulvar carcinoma cell lines A431 and CAL-39 was examined." (PMID 37762008, 2023). "In A431 and CAL-39 vulvar carcinoma cells, GPER1 expression was mainly found in the cytoplasm and nuclei." (PMID 37762008, 2023). "Based on the findings of this study, the activation of GPER1 in vulvar carcinoma appears to have a tumor-suppressive effect." (PMID 37762008, 2023). "The results of the BrdU assay showed that GPER1 agonist G1 treatment decreased proliferation of the vulvar carcinoma cells A431 and CAL-39." (PMID 37762008, 2023). "The staining of the microarray indicates that GPER1 is consistently expressed in vulvar carcinoma, as evidenced by the presence of GPER1 staining in all samples." (PMID 37762008, 2023). "Further evidence is needed to better understand the function of GPER1 in vulvar carcinoma and to potentially utilize GPER1 activation in medical treatment." (PMID 37762008, 2023). "The impact of GPER1 activation/inhibition on this ability of vulvar carcinoma cells was assessed using the colony formation assay." (PMID 37762008, 2023). "Activation of GPER1 with GPER1 agonist G1 reduces the tumorigenic potential of the vulvar carcinoma cells." (PMID 37762008, 2023). "Using immune cytochemistry, which allows the visualization of molecular markers, it has been demonstrated that GPER1 is expressed in the cytoplasm and nuclei of vulvar carcinoma cells A431 and CAL-39." (PMID 37762008, 2023). "In this work, we aim to clarify what role GPER1 plays in vulvar cancer, tumor-promoting or tumor-suppressive." (PMID 37762008, 2023). "Little is known about the function of GPER1 in vulvar carcinoma." (PMID 37762008, 2023). "This study aims to examine the function of GPER1 in vulvar carcinoma." (PMID 37762008, 2023). "Additionally, there may be a correlation between GPER1 expression and malignancy grade of vulvar carcinoma." (PMID 37762008, 2023). "Therefore, we checked whether the biological effect of G1 occurs through GPER1 in vulvar carcinoma cells." (PMID 37762008, 2023). "By conducting Western blot analysis, changes in protein expression of estrogen receptors in vulvar carcinoma cells A431 and CAL-39 were examined after GPER1 activation/inhibition." (PMID 37762008, 2023). "In the A431 vulvar carcinoma cell lines, there were no changes in the expression of GPER1, ERα, and ERβ after treatment with G1 or G36, compared with control." (PMID 37762008, 2023). "GPER1 was detected in A431 and CAL-39 vulvar carcinoma cells using immune cytochemical staining." (PMID 37762008, 2023). "Localization of GPER1 in A431 and CAL-39 vulvar carcinoma cells was examined by immunofluorescence." (PMID 37762008, 2023). "The GPER1 antagonist G36 did not have any significant effect on the vulvar carcinoma cells at all doses compared to the ethanol control." (PMID 37762008, 2023). "The GPER1 antagonist G36 did not have significant effects on vulvar carcinoma cells." (PMID 37762008, 2023).
Waldenström Macroglobulinemia (1 paper, 2022). "Here, we show that GPER1 is significantly upregulated in tumor cells from different cohorts of Waldenström Macroglobulinemia (WM) patients compared to normal B cells." (PMID 36096954, 2022).
cancer (278 papers, 2008 to 2026). A tumor composed of atypical neoplastic, often pleomorphic cells that invade other tissues. "GPER1 is expressed in various cancers, with higher levels of GPER expression linked to tumor development in some female reproductive system neoplasms and associated with poor prognosis." (PMID 39684286, 2024). "Cox regression analysis of 35 cancers showed that GPER1 expression in 11 cancers was significantly associated with OS." (PMID 37921845, 2023). "In fact, the binding of E2, BPA, and DES to GPER1 activates cancer-related pathways, which are associated with increased cell proliferation and migration, dependent on the CRC tumor microenvironment." (PMID 36384894, 2023). "Our findings also showed that the AUC of GPER1 Receiver operator characteristic (ROC) was more than 0.7 in 21 cancers, indicating that GPER1 had a wide diagnostic efficacy in cancer." (PMID 37921845, 2023). "Recent years of research accumulation have progressively unveiled the multifaceted association between GPER1 and various aspects of cancer pathogenesis, further accentuating its potential as a therapeutic target for cancer." (PMID 37921845, 2023). "Studies carried out with GPER1-deficient mice, or exploiting GPER1-selective agonists, have shown that GPER1-signaling plays an important function in various physio-pathological conditions, including cancer." (PMID 37759449, 2023). "Our results found that GPER1 was associated with gene expression of these immune components various cancers." (PMID 37921845, 2023). "One study revealed that GPER1 overexpression and upregulation of the cancer suppressor gene beclin-1 in ESCC is associated with poor prognosis." (PMID 36060947, 2022). "GPER1 has also been implicated in cancer and stroma-related inflammation, a hot topic in cancer research, and a preferential therapeutic target in cancer treatment." (PMID 33133022, 2020). "In particular, miR-338-3p levels were reduced by E2 or G1 through GPER1, causing an increased cancer cell progression mediated by the augmented expression of its target gene, the proto-oncogene c-Fos." (PMID 33374170, 2020). "In a number of cancer types, like breast, endometrial and ovarian tumors, high levels of GPER1 have been associated with larger tumor size, Her-2 expression and metastasis, as well as with poor survival." (PMID 33374170, 2020). "The immunomodulatory effect of GPER1 has also been implicated in cancer immune tolerance, although data for potential therapeutic implications in this field are limited." (PMID 33133022, 2020). "GPER-1 can also induce expression of cancer-associated fibroblasts (CAFs) in tumor microenvironment." (PMID 27314054, 2016). "However, this also implies that GPER1 itself plays a key role in the development and progression of several cancers and that mutations can cause failure or alteration of this role." (PMID 37921845, 2023). "This study analysed genetic mutations of GPER1 in pan-cancer using the cBioPortal online tool." (PMID 37921845, 2023). "Consequently, this study aims to investigate the diagnostic and prognostic significance of GPER1 expression in the context of pan-cancer." (PMID 37921845, 2023). "In addition, the activation of GPER1 is strongly associated with estrogen signaling and the proliferation of both types of cancer." (PMID 36231664, 2022). "The opposite effects of GPER-1 in cancer cells may be associated with the epigenetic of GPER-1, such as the SNPs and histone acetylation." (PMID 27314054, 2016). "GPER-1 may also act through direct or indirect association with other estradiol-responsive receptors or inflammation-related receptors, and its levels may also be affected by the activity of cancer-associated fibroblasts (CAFs) in the tumor microenvironment." (PMID 39936103, 2025). "In addition, lower expression of GPER1 was also associated with poor prognosis, so GPER1 may also be a prognostic marker for this cancer type." (PMID 38672656, 2024).
cancer (continued). "Conflicting reports exist for the role estrogen-mediated GPER1 activation in cancer progression plays." (PMID 38886847, 2024). "First, we compared the fold change in expression of the ER-related receptors ESR1, ESR2, ESRRA, ESRRB, ESRRG, and GPER1 in the four female cancers." (PMID 38582811, 2024). "E2 has been shown to reduce cancer cell migration and estrogenic signaling, an effect that is dependent on GPER1 activity; of note, these changes are reversed by GPER1 silencing under hypoxic conditions." (PMID 38886847, 2024). "In a comprehensive bioinformatic analysis of the role of GPER1 in cancer, an elevated expression of GPER1 was observed in HNSCC, compared to the normal tissue, suggesting its diagnostic potential." (PMID 38672656, 2024). "While the regulatory role of GPER1 in tumor cell proliferation has been explored in various cancers, including HCC, there has been less study on its effects on immune cell proliferation." (PMID 39582864, 2024). "Other studies confirmed GPER1 expression to be reduced by hypermethylation in various cancers, like breast cancer." (PMID 39796024, 2024). "Considering the role of GPER1 in cancer pathophysiology, it has been suggested as a potential target for cancer therapy." (PMID 39252786, 2024). "Recent reports highlight a significant correlation between GPER1 and the progression of diverse cancers." (PMID 37921845, 2023). "The correlation between GPER1 expression level and immune components in pan-cancer were inferred via the TISIDB database." (PMID 37921845, 2023). "In contrast, the role of ERs discovered later, including ERβ and G-protein-coupled ER (GPER1), in cancer is less well understood, but the current state of knowledge indicates them to have a considerable impact on both cancer development and progression." (PMID 37345182, 2023). "Among the 11 cancers selected for analysis, high or low GPER1 expression showed a significant effect on OS." (PMID 37921845, 2023). "GPER1 has been found expressed in cancers, where its role has been extensively investigated especially in solid tumors, in which a dualistic tumor-promoting or -suppressive function emerges, depending on the tumor type." (PMID 37759449, 2023). "In summary, pan-cancer analysis of GPER1 in our study showed that it was widely expressed in human tissues and organs and that its expression differs from normal tissue in various cancers." (PMID 37921845, 2023). "G protein-coupled estrogen receptor 1 (GPER1) activation is emerging as a promising therapeutic strategy against several cancer types." (PMID 37759449, 2023). "GPER1’s mRNA and protein were found to be widely expressed in diverse tissues, forming the basis for pan-cancer analyses." (PMID 37921845, 2023). "For the purpose of evaluating the prognostic value of GPER1 in pan-cancer, Kaplan–Meier (K-M) analysis was conducted." (PMID 37921845, 2023). "Our study findings demonstrate that across the 10 studied cancer types, GPER1 exhibits high methylation in 5 cancers (BRCA, ESCA, HNSC, LUAD, and UCEC) and low methylation in 3 cancers (KIRC, KIRP, and PAAD)." (PMID 37921845, 2023). "Unfortunately, by interfering with cellular dynamics, GPER1 becomes involved in the development and progression of different types of cancer." (PMID 36835454, 2023). "Early stage and well differentiated cancers strongly expressed GPER1, which was found in 83.1% of all malignant tumors." (PMID 37345182, 2023). "This complexity is also compounded by differences in the genetic correlation between GPER1 and the same immune component among various tumours, suggesting that GPER1 has different effects on tumour immunity in different cancers." (PMID 37921845, 2023). "The discovery of GPER1 selective agonists and antagonists has indeed provided insights into GPER1’s pathophysiological role and its involvement in cancer biology." (PMID 37759449, 2023).
cancer (continued). "This study obtained the methylation data of GPER1, which have been considered significant in the survival analysis with corresponding normal tissues, for 10 cancers using the MethSurv database." (PMID 37921845, 2023). "Our results are consistent with previous studies showing that activation of GPER1 by G1 exerts an inhibitory effect on various cancer cells." (PMID 37762356, 2023). "This biological effect is consistent with the addition of a GPER1 antagonist such as G1, which blocks the effects of E2 in cancer cells." (PMID 36231664, 2022). "Activating G protein-coupled estrogen receptor 1 (GPER1) is an attractive therapeutic strategy for treating a variety of human diseases including cancer." (PMID 36096954, 2022). "It is a well-described phenomenon that GPER1 signaling promotes tumor progression, helps cancer cells to obtain stem cell-like properties, and can mediate therapy resistance." (PMID 35337112, 2022). "Given the role of GPER1 signaling in cardiorenal disease and carcinogenesis, improving our understanding of the cardiovascular and renal responses to GPER1 will open another avenue to improve the care provided to cancer patients." (PMID 35327604, 2022). "Estrogen binds to estrogen receptors (ER) or G protein-coupled estrogen receptor 1 (GPER1) to regulate gene transcription and to promote cancer cell pathways." (PMID 34298609, 2021). "GPER1 is a membrane estrogen receptor that regulates cell growth, migration, apoptotic cell death, and other cancer-related biological functions." (PMID 33425895, 2020). "Overall, this positions GPER1 as a good prognostic and/or therapeutic target in several cancers, where the tumor microenvironment is critical for tumor expansion." (PMID 33133022, 2020). "The research produced in this field in the last 15 years is now reaching maturity and GPER1 targeting is now also studied as a novel therapeutic approach in cancer, cerebrovascular, metabolic, and neurodegenerative diseases." (PMID 33133022, 2020). "Previous studies have reported that the G protein-coupled estrogen receptor-1 (GPER, formerly known as GPR30) was associated with disease progression in cancer patients." (PMID 33042020, 2020). "G protein coupled estrogen receptor (GPER1) is a membrane estrogen receptor, belonging to the seven-transmembrane G protein-coupled receptors family, and has important biological functions in cancer." (PMID 33425895, 2020). "TCGA data analysis strongly supported our findings that high AMF-secreting GPER-1-positive cancer cells initially and intrinsically have the advantages of growth and malignancy." (PMID 30836961, 2019). "Studies using selective agonists and antagonists for estrogen receptors, has made it more evident that GPER-1 has a major role to play in resistance to chemotherapy in ER positive breast cancers and also other cancers such as ovary and endometrium." (PMID 31749762, 2019). "More studies to reveal the functions and mechanisms of GPER-1 in the other system cancers are warranted." (PMID 27314054, 2016). "Majority of the study results addressed that activation of GPER-1 by estrogen and G-1 results in the downstream signals and target genes activation, which promotes the proliferation, migration, and invasion of cancer cells." (PMID 27314054, 2016). "Since the function and mechanisms of GPER-1 are still unclear, more researches and clinical studies are strongly warranted to clarify the different function and mechanisms in different cancer types and conditions." (PMID 27314054, 2016). "Despite the fact that GPER-1 can mediate the proliferative effects of estrogen in many estrogen-related cancers, we and others have demonstrated that GPER-1 can inhibit cell proliferation in different cell systems." (PMID 23849542, 2013). "GPER-1 expression was observed in 83.1% of malignant tumors and was higher in early stage cancers and tumors with high histological differentiation." (PMID 23849542, 2013).
cancer (continued). "Tumor suppressors are known to be inactivated during cancer progression which was also observed for GPER-1." (PMID 23849542, 2013). "Additionally, the activation of GPER1 signaling has been shown to regulate the proliferation of tumor cells in various types of cancer." (PMID 39582864, 2024). "Besides its expression in normal tissues, GPER1 has also been found in many types of cancers/cancer cell lines." (PMID 39252786, 2024). "Furthermore, the expression of GPER1 differs significantly between normal or paracancerous tissues in numerous cancers, providing easy access to samples for clinical diagnosis." (PMID 37921845, 2023). "This study comprehensively investigated the multifaceted role of GPER1 across various cancers." (PMID 37921845, 2023). "Collectively, our results provide the first demonstration that (xeno)estrogens might trigger key cancer-prone lesions and point GPER1 to an important regulatory protein mediating CA, w-CIN, and aneuploidy in a non-classical hormone-regulated colon cell system." (PMID 36384894, 2023). "As a result, GPER1 is emerging as a novel potential therapeutic target for cancer treatment." (PMID 37759449, 2023). "Notably, its AUC exceeded 0.9 in nine cancers, suggesting that GPER1 has great detective ability and reliable efficiency, allowing its use as a diagnostic biomarker in these cancers." (PMID 37921845, 2023). "Our findings showed that GPER1 expression was positively correlated with TILs in majority cancers." (PMID 37921845, 2023). "We further compared the GPER1 methylation levels among the identified cancers." (PMID 37921845, 2023). "In some cancers, GPER1 was correlated with immune components with some consistency." (PMID 37921845, 2023). "More studies, including such correlating GPER1 protein expression in EC tissue with patient survival, and in vivo approaches examining the effects of GPER1 modulation with specific antagonists in animal models will be necessary to elucidate the role of GPER1 in this cancer entity." (PMID 37345182, 2023). "Furthermore, the study explored GPER1’s epigenetic landscape, highlighting methylation patterns that exhibited heterogeneity across cancers, contributing to its regulatory complexity." (PMID 37921845, 2023). "Importantly, aberrant GPER1 expression can be used to predict cancer progression and poor survival in patients with breast and gynecological cancers." (PMID 36835454, 2023). "This also implies the intricate involvement of GPER1 in cancer development." (PMID 37921845, 2023). "Interestingly, GPER1 expression correlated with diverse overall survival outcomes in distinct cancer types." (PMID 37921845, 2023). "Accordingly, GPER1 genetic mutations promoted a significant decrease in OS, disease-free survival (DFS), disease-specific survival (DSS) and progression-free survival (PFS) (all p < 0.001) in pan-cancer." (PMID 37921845, 2023). "Consequently, the development of cancer treatment strategies targeting GPER1 has garnered significant attention." (PMID 37921845, 2023). "The clinical relevance of GPER1 expression remains controversial, with some data showing that the downregulation of GPER1 is associated with cancer progression, while others suggest that lack of GPER1 expression is a good prognosis factor." (PMID 37834225, 2023). "Survival analysis showed that GPER1 was correlated with the prognosis of 11 cancer types." (PMID 37921845, 2023). "Whether GPER1 promotes or suppresses cancer lacks a definite conclusion, as GPER1 methylation involves a series of subsequent changes, encompassing downstream signaling pathways and immune modulation." (PMID 37921845, 2023). "The G protein–coupled estrogen receptor-1 (GPER) has distinct functions from those of the classic estrogen receptors ERα/β and its activation by specific agonists has tumor-suppressive roles in several cancers." (PMID 37035582, 2023). "Except for DLBC, methylation data of GPER1 for 10 cancers and normal tissues were obtained." (PMID 37921845, 2023).